CABP4 (calcium binding protein 4)
Description:
Involved in normal synaptic function through regulation of Ca(2+) influx and neurotransmitter release in photoreceptor synaptic terminals and in auditory transmission. Modulator of CACNA1D and CACNA1F, suppressing the calcium-dependent inactivation and shifting the activation range to more hyperpolarized voltages (By similarity).
Synonyms: CSNB2B; CRSD
Tractability: PROTAC: ubiquitination databases record sites on it.
Gene: Protein-coding gene on chromosome 11 (67,452,406 to 67,461,752, forward strand). Ensembl gene ENSG00000175544.
Subcellular location: Cytoplasm; Presynapse
Gene Ontology:
Molecular function: transmembrane transporter binding; calcium channel regulator activity; calcium ion binding
Biological process: visual perception; phototransduction; sensory perception of sound; signal transduction
Cellular component: cytoplasm; cytosol; extracellular region; presynapse; synapse; terminal bouton
Genetic constraint (gnomAD): Loss-of-function variants: 30 observed, 30.25 expected, observed/expected ratio (o/e) 0.99, 90% interval 0.74 to 1.35. The upper end of that interval is the gene's LOEUF score, 1.35, which puts it in group 5 of 6, group 1 being the genes least tolerant of losing a copy. Missense variants: 424 observed, 388.73 expected, observed/expected ratio (o/e) 1.09, 90% interval 1.01 to 1.18. Synonymous variants: 161 observed, 157.76 expected, observed/expected ratio (o/e) 1.02, 90% interval 0.9 to 1.16.
Homologues: Orthologues: chimpanzee CABP4 (99% identical), macaque CABP4 (93% identical), dog CABP4 (77% identical), pig CABP4 (76% identical), mouse Cabp4 (75% identical), guinea pig CABP4 (74% identical), rat Cabp4 (73% identical), tropical clawed frog cabp4 (44% identical), zebrafish CABP4 (40% identical), Caenorhabditis elegans cal-1 (22% identical), Caenorhabditis elegans cal-3 (22% identical), Caenorhabditis elegans E02A10.3 (21% identical), and 9 more. Paralogues in human: CABP2 (44% identical), CABP1 (37% identical), CABP5 (35% identical), CALN1 (25% identical), CABP7 (24% identical), CALM1 (24% identical), CALM2 (24% identical), CALM3 (24% identical), CALML3 (23% identical), CETN1 (21% identical), CETN2 (21% identical), CALML6 (20% identical), and 8 more.
Diseases named in the same sentence as CABP4 in open-access papers:
CABP4 is named in the same sentence as 26 diseases in open-access papers, as found by Europe PMC text mining. Sharing a sentence is not in itself a finding about the gene and the disease. The quoted sentences say what the papers report.
congenital stationary night blindness (10 papers, 2010 to 2025). "Mutations within CaBP4 are associated with a range of neuronal pathologies, such as congenital stationary night blindness, cone–rod dystrophy, and autosomal dominant nocturnal frontal lobe epilepsy (ADNFLE)." (PMID 39936944, 2025). "Cabp4 encodes a calcium binding protein expressed in bipolar cells in the eyes leading to congenital stationary night blindness if the gene is mutated." (PMID 36386828, 2022). "Rod and cone synaptic function is markedly diminished in CaBP4 knockout mice, and loss-of function mutations in CaBP4 cause congenital stationary night blindness and other visual disorders in humans." (PMID 33173469, 2020). "Functional research of the CaBP4 mutations in congenital stationary night blindness have shown that the regulatory function of the mutant proteins is weaker compared to the wild type proteins." (PMID 29108277, 2017). "Findings consistent with an important role for CaBP4 in the regulation of phototransduction have come from the study of a CaBP4 mouse knock-out and also the presence of mutations in human CaBP4 and in CaV1.4, which cause retinal disorders including congenital night blindness." (PMID 25447549, 2015).
visual disorders (4 papers, 2010 to 2025). "Clinically relevant mutations in CaBPs are associated with a range of pathogenic phenotypes, including autosomal recessive hearing loss caused by mutations in CaBP2, as well as various visual disorders, dystrophies, and frontal lobe epilepsy linked to CaBP4 mutations." (PMID 39936944, 2025). "In addition, mutation in CaBP4 in humans leads to congenital visual disorders." (PMID 20426809, 2010).
autosomal dominant nocturnal frontal lobe epilepsy (3 papers, 2017 to 2025). A seizure disorder characterized by intermittent dystonia and/or choreoathetoid movements that occur during sleep. "A new missense mutation has been found in the CABP4 gene encoding the neuronal binding protein Ca2+4 (CaBP4), including 11 individuals diagnosed with ADSHE a (p.G155D) in the Ca2+4 binding protein (CABP4) in a Chinese family with autosomal dominant nocturnal frontal lobe epilepsy." (PMID 34769124, 2021).
night blindness (3 papers, 2010 to 2024). Inability to see clearly in dim light. "Hence it has been suggested that iCSNB can be a misnomer, particularly in the case of CABP4-associated disease, where night blindness is seldom, if ever, reported." (PMID 38206458, 2024). "The patient saw better in dim light, confirming that night blindness is not a feature of CABP4-associated disease." (PMID 38206458, 2024). "Our patient’s preference for dim lighting supports the notion that night blindness is not a typical feature of CABP4-associated disease, as noted in several previous publications." (PMID 38206458, 2024). "They considered these patients as having a newly described disorder however, primarily because patients who bore CaBP4 mutations did not experience night blindness." (PMID 36982165, 2023). "In order to resolve the clinical diagnosis of individuals with CABP4 mutations, a retrospective analysis was conducted, and it was found that all but one of the patients shared similar clinical features, and none included night blindness." (PMID 36982165, 2023). "The authors of that paper noted that two of the three families reported so far with CABP4 mutations lacked nyctalopia in their clinical presentation and suggested that the term congenital cone-rod synaptic disorder be used as a more accurate name than CSNB2 for this subtype." (PMID 20157620, 2010).
Retinal dystrophy (3 papers, 2024 to 2025). Retinal dystrophy is an abnormality of the retina associated with a hereditary process. "For CABP4-associated disease, it has been suggested that “congenital cone–rod synaptic disorder” (OMIM #610427) should be used or “CABP4-related retinal dystrophy” or “CABP4-related disease”." (PMID 38206458, 2024).
achromatopsia (2 papers, 2024 to 2025). Achromatopsia (ACHM) is a rare autosomal recessive retinal disorder characterized by color blindness, nystagmus, photophobia, and severely reduced visual acuity due to the absence or impairment of cone function. "For example, CABP4‐associated disease can present with similar symptoms to achromatopsia (photophobia, impaired vision and a stable course), but the ERG phenotype is quite different (with an electronegative dark‐adapted ERG seen in CABP4‐disease)." (PMID 40013354, 2025).
congenital nystagmus (1 paper, 2020). Nystagmus present at birth or caused by lesions sustained in utero or at the time of birth. "Additionally, SLC38A8 contributes to congenital nystagmus, and RIMS1 and CABP4 are associated with dystrophy and synaptic disorder of cone-rod, respectively." (PMID 33330132, 2020).
fascioliasis (1 paper, 2021). A parasitic infection that is caused by liver flukes, usually Fasciola hepatica, of sheep, goats, and cattle. "In this study, goat monocytes showed higher levels of IL-2 and IFN-γ cytokines in response to rFg-CaBP4 protein, suggesting that these cytokines may be linked to non-protective immune responses against fascioliasis." (PMID 34022913, 2021).
glioma (1 paper, 2023). A benign or malignant brain and spinal cord tumor that arises from glial cells (astrocytes, oligodendrocytes, ependymal cells). "Some genes, such as CABP4, DUSP10, LPIN3, were reported for the first time to be associated with glioma." (PMID 37662954, 2023).
Leber congenital amaurosis (1 paper, 2010). Leber congenital amaurosis (LCA) is a retinal dystrophy defined by blindness and responses to electrophysiological stimulation (Ganzfeld electroretinogram (ERG)) below threshold, associated with severe visual impairment within the first year of life. "The four patients had a clinical presentation highly reminiscent of Leber Congenital Amaurosis (LCA, congenital onset, nystagmus, severe visual impairment, and severely diminished or extinguished ERG), which expands the spectrum of the CABP4-associated phenotype." (PMID 20157620, 2010).
myopia (1 paper, 2024). "Surprisingly, genes associated with retinal disorders (CLUL1, VSX1, RD3, RS1, and CABP4) and a cone pigment (OPN1LW) were identified in choroid but not retina of progressing chick myopia." (PMID 39028695, 2024).
Optic disc pallor (1 paper, 2021). A pale yellow discoloration of the optic disc (the area of the optic nerve head in the retina). "Optic disc pallor has not been described in cases of iCSNB due to CABP4 or CACNA2D4 mutations." (PMID 33668843, 2021).
parasitic infection (1 paper, 2021). "This indicated that the rFg-CaBP4 protein plays a vital role in the inhibition of parasitic infection by presenting antigen peptides to monocytes, and results in strong adaptive immune responses through increased levels of MHC-II molecule expression." (PMID 34022913, 2021).
retinal disease (1 paper, 2021). "CABP4, a retinal disease gene and direct transcriptional target of CRX showed a similar trend." (PMID 33513359, 2021).
urothelial carcinoma of the bladder (1 paper, 2022). "CABP4 has been reported to be associated with the TME of urothelial carcinoma of the bladder currently." (PMID 36311731, 2022).
retinal disorder (6 papers, 2010 to 2025). Any disease or disorder of the retina. "A spontaneously occurring mutation in CaBP4 (Calcium binding protein 4) was identified in the Whippet breed of dog and is a model for human CaBP4 related retinopathies." (PMID 40461693, 2025). "CABP4 is associated with retinopathy and plays an important role in visual perception." (PMID 36311731, 2022). "We hypothesize that CABP4 and RORB might be involved in the interaction of NK cells and photoreceptor cells, which can be influenced by B7 expression and might participate in symptoms associated with UVM, like retinopathy or loss of photoreceptor." (PMID 36311731, 2022).
CABP4 also shares sentences with these, for which no sentence is quoted: infection (2 papers); Photophobia (2); autosomal recessive hearing loss (1); cone dystrophy (1); frontal lobe epilepsy (1); hyperopia (1); macular degeneration (1); Macular dystrophy (1); Nystagmus (1); retinitis pigmentosa (1).